DUSP10 (dual specificity phosphatase 10)
Diseases named in the same sentence as DUSP10 in open-access papers (continued):
Sharing a sentence is not in itself a finding about the gene and the disease.
glioma (3 papers, 2022 to 2023). A benign or malignant brain and spinal cord tumor that arises from glial cells (astrocytes, oligodendrocytes, ependymal cells). "In the present study, we found enhanced DUSP10 expression in glioma, which was also associated with a poor prognosis." (PMID 36713584, 2022). "The GEO glioma datasets also indicated that high expression of DUSP10 was closely associated with adverse clinical outcomes in these patients." (PMID 36713584, 2022). "Using LinkedOmics, we obtained the top 100 genes that were positively or negatively associated with DUSP10 expression in glioma based on TCGA cohort (–C)." (PMID 36713584, 2022). "We plan to perform more in vivo and in vitro experiments to assess the function and the potential molecular mechanisms underlying the effects of DUSP10 in tumor progression and tumor microenvironment regulation of glioma." (PMID 36713584, 2022). "Herein, we sought to examine the expression and the underlying carcinogenic mechanisms of DUSP10 action in glioma." (PMID 36713584, 2022). "By analyzing TCGA data, hypomethylation of the DUSP10 promoter was found to be associated with its elevated expression in glioma tissues." (PMID 36713584, 2022). "Furthermore, univariate and multivariate Cox analyses identified DUSP10 expression as an independent prognostic risk factor for glioma." (PMID 36713584, 2022). "Thus, we aimed to assess the underlying mechanism of DUSP10 action in the progression of gliomas and its potential immune activation and sensitivity to immunotherapeutic responses in these patients." (PMID 36713584, 2022). "The expression of DUSP10 and its correlation with clinical characteristics, prognosis, immune cell infiltration, and immunomodulator-related molecules expression, along with its potential functions and mechanisms underlying glioma, were assessed using public databases." (PMID 36713584, 2022). "Some genes, such as CABP4, DUSP10, LPIN3, were reported for the first time to be associated with glioma." (PMID 37662954, 2023). "The results showed that glioma patients with the higher DUSP10 expression had poor overall survival (OS), disease-specific survival (DSS), and progression-free survival (PFS) (–C)." (PMID 36713584, 2022). "Taken together, these results suggested that DNA methylation is an important mechanism modulating DUSP10 expression in glioma." (PMID 36713584, 2022). "In the present study, DUSP10 was found to be highly expressed across multiple cancer types, especially glioma." (PMID 36713584, 2022). "ROC analysis demonstrated that DUSP10 expression was a reliable marker for predicting the clinical outcomes in glioma." (PMID 36713584, 2022). "In the future, we plan to assess the function of DUSP10 in tumor progression and tumor microenvironment regulation in glioma." (PMID 36713584, 2022). "Univariate Cox analysis showed that high DUSP10 expression was a potential independent marker of poor prognosis in glioma." (PMID 36713584, 2022). "We examined the methylation status of the DUSP10 promotor region in glioma using the sequencing data of TCGA-glioma cohort." (PMID 36713584, 2022). "We also observed a strong positive correlation between immunomodulator-related genes and DUSP10 expression in glioma." (PMID 36713584, 2022). "Given that DUSP10 is upregulated in glioma, we knocked down DUSP10 expression using short interfering RNA (siRNA), and its efficiency was verified by a real-time RT-PCR assay." (PMID 36713584, 2022). "With the use of TCGA and Genotype-Tissue Expression (GTEx) databases, the expression of DUSP10 was found to be enhanced in various cancers, especially glioma." (PMID 36713584, 2022). "In this study, we observed that DUSP10 expression in glioma correlated positively with the abundance of B cells, CD4+ T cells, CD8+ T cells, neutrophils, macrophages, and dendritic cells." (PMID 36713584, 2022).
glioma (continued). "Quantitative real-time polymerase chain reaction (RT-qPCR), cholecystokinin octapeptide (CCK8), and transwell assays were performed to measure the effect of the knockdown of DUSP10 in glioma cell growth and migration." (PMID 36713584, 2022). "Collectively, these results demonstrated that the expression of DUSP10 correlated positively with glioma cell proliferation and migration." (PMID 36713584, 2022). "The immunohistochemical images obtained from HPA showed that DUSP10 expression was lower in normal brain tissue relative to glioma tissues." (PMID 36713584, 2022). "The following bioinformatics analysis showed a close relationship between DUSP10 expression and immune progression, which indicated the role of DUSP10 in the glioma immune microenvironment." (PMID 36713584, 2022). "In this study, our bioinformatics analysis results showed that DUSP10 expression increased with the increasing degree of malignancy of glioma." (PMID 36713584, 2022). "Herein, we unravel the biological functions of DUSP10 in glioma and offer a potential strategy for the diagnosis and treatment of these patients." (PMID 36713584, 2022). "In the in vitro study, we demonstrated that DUSP10 upregulation was mediated by DNA demethylation that drove glioma malignancy." (PMID 36713584, 2022). "We used the Chinese Glioma Genome Atlas (CGGA) database to validate the grade and prognosis of DUSP10 in glioma, and we found that DUSP10 expression was correlated with tumor grade and adverse clinical outcomes (–H)." (PMID 36713584, 2022). "High expression of DUSP10 correlated significantly with the clinical outcomes and histological type in glioma." (PMID 36713584, 2022). "We also found a strong positive correlation between immunomodulator-related genes and DUSP10 expression in glioma." (PMID 36713584, 2022). "Moreover, DUSP10 expression in normal human astrocytes was lower than that in human glioma cell lines (U251, A172, and T98G), as evidenced by qRT-PCR analysis." (PMID 36713584, 2022). "We also established a nomogram to integrate DUSP10 expression as a glioma biomarker." (PMID 36713584, 2022). "Increased DUSP10 expression correlated significantly with clinical features in glioma." (PMID 36713584, 2022). "Patients showing higher DUSP10 expression in glioma were >60 years." (PMID 36713584, 2022). "DUSP10 expression in glioma was significantly higher than that in normal brain tissues." (PMID 36713584, 2022). "Finally, in vitro, functional experiments showed that knocking down DUSP10 inhibited glioma cell proliferation and migration and promotes glioma cell apoptosis glioma cells." (PMID 36713584, 2022). "Furthermore, the HPA immunohistochemistry images showed that high-grade glioma tissues had higher levels of DUSP10 than low-grade glioma tissues." (PMID 36713584, 2022). "Our findings suggested that DUSP10 was a prognostic marker of glioma and might be a potential target for the treatment of these patients." (PMID 36713584, 2022). "However, information available on the expression, regulation, clinical significance, and biological function of DUSP10 in glioma is scarce." (PMID 36713584, 2022). "DNA methylation level of DUSP10 also correlated negatively with poor prognosis in glioma." (PMID 36713584, 2022). "Next, we screened the potential signaling pathways related to DUSP10 expression in glioma by GSEA." (PMID 36713584, 2022). "However, future experimental validation of the biological significance and potential mechanism of DUSP10 action in glioma is needed." (PMID 36713584, 2022). "Moreover, immunohistochemical images of the normal brain tissue, low-grade glioma, and high-grade glioma acquired from the Human Protein Atlas (HPA) database confirmed the elevated protein levels of DUSP10, which increased with tumor grade." (PMID 36713584, 2022). "Clinical characteristics of glioma patients in TCGA dataset according to DUSP10 expression." (PMID 36713584, 2022).
glioma (continued). "High DUSP10 expression indicated adverse clinical outcomes in glioma patients." (PMID 36713584, 2022). "This is the first study to assess the correlation between DUSP10 and glioma." (PMID 36713584, 2022). "Finally, using the Tumor Immunotherapy Gene Expression Resource (TIGER) database, we found that DUSP10 expression was positively correlated with T-cell dysfunction and T-cell exhaustion in glioma." (PMID 36713584, 2022). "Finally, we showed that DUSP10 expression may affect the clinical outcomes of glioma patients by mediating immune cell infiltration." (PMID 36713584, 2022). "Furthermore, DUSP10 might be involved in the progression of glioma by regulating the function of immune-infiltrating cells and immune response-related signaling pathways." (PMID 36713584, 2022). "Therefore, we speculated that DUSP10 expression could serve as a predictor for the clinical prognosis of glioma patients." (PMID 36713584, 2022). "DUSP10 inhibited glioma cell proliferation may be by promoting glioma cell apoptosis glioma cells." (PMID 36713584, 2022). "Furthermore, DUSP10 expression in glioma correlated negatively with its DNA methylation levels." (PMID 36713584, 2022). "Our findings suggested that DUSP10 may serve as a potential prognostic biomarker in glioma." (PMID 36713584, 2022). "Subsequently, we utilized the three independent LGG cohorts, including the TCGA, Chinese Glioma Genome Atlas (CGGA), and GSE61374 cohorts, to further inspect the prognostic significance of DUSP10 in LGG." (PMID 37387540, 2023). "More importantly, DUSP10 expression correlated positively with the infiltration of B cells, CD4+ T cells, CD8+ T cells, neutrophils, macrophages, and dendritic cells in glioma." (PMID 36713584, 2022). "Thus, DUSP10 might represent a potential target in the treatment of glioma." (PMID 36713584, 2022). "However, the relationship between DUSP10 expression and the clinicopathological characteristics of glioma patients, as well as the prognostic significance of DUSP10 expression for glioma, has not been well studied." (PMID 36713584, 2022). "To date, no study has examined whether DUSP10 expression correlates with glioma progression." (PMID 36713584, 2022).
influenza infection (3 papers, 2019 to 2022). "Of them, many had relevance in influenza infection such as genes responsible for virus entry (Anxa1/2, Cd14), interferon signaling (Dusp10, Tnfsf13), or prostaglandin synthesis (Ptgs1/2)." (PMID 35629310, 2022). "The role of DUSP10 in respiratory viral infection has also been examined in vivo: DUSP10 knock out mice infected with influenza had elevated levels of IL-6 in bronchoalveolar lavage (BAL) than wild-type mice." (PMID 30764493, 2019). "DUSP10 knock out mice have decreased numbers of virus specific CD4+ cells and CD8+ cells in the lung in response to influenza infection." (PMID 30764493, 2019). "On the other hand, DUSP10 limits production of type I IFN by macrophages infected with influenza virus, leading to a more rigorous IFN response to influenza infection in DUSP10 −/− mice, better control of viral replication and increased survival." (PMID 31159473, 2019).
atherosclerosis (2 papers, 2019 to 2021). A disease characterized by the build-up of fatty material and calcium deposition in the arterial wall resulting in partial or complete occlusion of the arterial lumen. "DUSP10 has been also proposed as a target for therapeutic treatment of atherosclerosis, since DUSP10 inhibition reduces NF-κB-induced TNF-α expression and increases TGF-β1 levels in this disease." (PMID 30939861, 2019). "It is important to note that the expression of DUSP10 is elevated in various diseases, such as atherosclerosis, which may be the case in other pathophysiological conditions induced by the over-activation of AT1-R." (PMID 34944046, 2021).
Cluster headache (2 papers, 2022 to 2025). A type of headache characterized by repeated attacks of unilateral pain lasting 15 to 180 minutes and associated with local autonomic signs. "The four cluster headache susceptibility loci that were identified by this GWAS were rs113658130 near LINC01877/SATB2 (SATB homeobox 2), rs4519530 in MERTK, rs12121134 near LINC01705/DUSP10 (Dual Specificity Phosphatase 10), and rs11153082 in FHL5." (PMID 39560176, 2025).
glucose metabolism disorder (2 papers, 2020 to 2025). "microRNA-450a-5p could inactivate the insulin signal pathway by targeting the inhibited Dual Specificity Phosphatase 10 (DUSP10) and inducing IR and glucose metabolism disorders in vitro cultured hepatocytes and adipocytes." (PMID 39912972, 2025).
ischemia (2 papers, 2024 to 2025). A hypoperfusion of the BLOOD through an organ or tissue caused by a PATHOLOGIC CONSTRICTION or obstruction of its BLOOD VESSELS, or an absence of BLOOD CIRCULATION. "Genes associated with the stress-activated MAPK pathway—such as Dusp3, Dusp10, Dusp14, Junb, and Fos—were also specifically upregulated after ischemia, which may enable astrocytes to manage heightened stress signals, regulate inflammatory responses, and initiate repair mechanisms." (PMID 40618091, 2025).
Sepsis (2 papers, 2019 to 2020). Sepsis is defined as life-threatening organ dysfunction caused by a dysregulated host response to infection. "At a log2FC>2 (adjusted P < 0.05) MAPK related genes F2rl1, Adm (marked as multi, as it was picked up for term searches “metabolic,” “hypoxia,” and “MAPK”), Mapk4, Gdf15, Dusp10, and Dusp8 were up-regulated in Isoflurane-Sepsis compared to only 2 genes in the Propofol-Sepsis group." (PMID 33392215, 2020).
acute myeloid leukemia (1 paper, 2019). Acute myeloid leukemia (AML) is a group of neoplasms arising from precursor cells committed to the myeloid cell-line differentiation. "Highly expressed DUSP10 is also found in a common bone marrow disease such as acute myeloid leukemia (AML) and its expression correlates with disease subtypes." (PMID 30939861, 2019).
Allergy (1 paper, 2018). An allergy is an immune response or reaction to substances that are usually not harmful. "Thus, it is conceivable that the decreased expression of DUSP10 in Th2 cells causes allergic diseases and/or is associated with the pathogenesis of chronic allergic disorders." (PMID 30315197, 2018). "We also analyzed the degree of AHR in the allergy-induced mice, which received Mock- or Dusp10-ILC2s, by measuring methacholine-induced airflow obstruction with a mechanical ventilator." (PMID 30315197, 2018). "Therefore, small molecules that upregulate DUSP10 or mimic DUSP10 function could be used as new therapeutic agents for the treatment of allergic diseases." (PMID 30315197, 2018).
Arthritis (1 paper, 2019). Inflammation of a joint. "In contrast, PAC1 (DUSP-2) deletion mice have reduced inflammatory responses in arthritis, whilst the deletion of MKP-5 (DUSP-10) results in marked changes in T- cell proliferation and in CD4+ and CD8+ function." (PMID 31336892, 2019).
autoimmune disease (1 paper, 2019). A disorder resulting from loss of function or tissue destruction of an organ or multiple organs, arising from humoral or cellular immune responses of the individual to their own tissue constituents. "Besides DUSP22 downregulation in SLE patients, other DUSPs (DUSP2, DUSP7, DUSP10, and DUSP12) are also downregulated or mutated in human autoimmune diseases." (PMID 31766293, 2019). "DUSP2, DUSP4, DUSP7, DUSP10, DUSP12, DUSP22, and DUSP23 are involved in human autoimmune diseases, including SLE." (PMID 31766293, 2019). "In addition, DUSPs are also involved in either human autoimmune diseases (DUSP2, DUSP7, DUSP10, and DUSP12) or T-cell activation (DUSP1, DUSP5, and DUSP14)." (PMID 31766293, 2019).
Autoimmunity (1 paper, 2019). The occurrence of an immune reaction against the organism's own cells or tissues. "MKP-5 (DUSP10) also regulates T cell responses and autoimmunity in mice." (PMID 31297117, 2019).
celiac disease (1 paper, 2013). An autoimmune genetic disorder with an unknown pattern of inheritance that primarily affects the digestive tract. "In this study, we identified DUSP10 to be significantly associated with celiac disease." (PMID 23936387, 2013). "These genes and pathways, including specific functions of DUSP10, together reveal a new potential biological mechanism that could influence the genesis of celiac disease, and possibly also other chronic disorders with an inflammatory component." (PMID 23936387, 2013).
chronic obstructive pulmonary disease (1 paper, 2019). A chronic and progressive lung disorder characterized by the loss of elasticity of the bronchial tree and the air sacs, destruction of the air sacs wall, thickening of the bronchial wall, and mucous accumulation in the bronchial tree. "In order to ensure that the role of DUSP10 is clinically relevant, its role in PBECs isolated from chronic obstructive pulmonary disease (COPD) patients was investigated." (PMID 30333178, 2019).
intestinal cancer (1 paper, 2023). "Additionally, inhibition of DUSP10 was reported to be associated with gut inflammation, which might lead to the early development of intestinal cancer." (PMID 36869385, 2023).
lung carcinoma (1 paper, 2019).
malaria (1 paper, 2019). Malaria is a serious and sometimes fatal disease caused by a parasite that commonly infects a certain type of mosquito which feeds on humans. "In T cells, DUSP10 down-regulates TCR-induced IFNγ-production, which was also observed in a murine malaria model during infection of DUSP10−/− mice with Plasmodium yoelii." (PMID 31159473, 2019).
meningioma (1 paper, 2019). A generally slow growing tumor attached to the dura mater. "DUSP10 is expressed in the majority of meningiomas of all grades, regulating cell proliferation and tumor progression." (PMID 30939861, 2019). "This tumorigenic phenotype is due to DUSP10 dephosphorylates p38, in which inactivation is determinant in the pathogenesis of meningiomas." (PMID 30939861, 2019).
multiple sclerosis (1 paper, 2019). A progressive autoimmune disorder affecting the central nervous system resulting in demyelination. "Authors suggest DUSP10 inhibition as a possible target for treating dysfunctional myelin deposition-associated diseases such as multiple sclerosis." (PMID 30939861, 2019). "Dusp10-deficient mice are resistant to experimental myelin-induced autoimmune encephalitis (EAE), an animal model of multiple sclerosis." (PMID 30939861, 2019).
myeloma (1 paper, 2020). "Moreover, a six-gene risk score model (ZNF486, EPHA5, RP11.326C3.15, DUSP6, DUSP10, and TRIAP1) for the prognostic prediction of PI-treated myeloma patients was developed by the random survival forest variable hunting (RSF-VH) algorithm." (PMID 33344452, 2020).
prostatic adenocarcinoma (1 paper, 2019). "The upregulation of DUSP10 by 1,25D occurs in primary prostatic adenocarcinoma, while DUSP10 expression is absent in PC cell lines derived metastases, leading to pro-carcinogenic inflammation." (PMID 30939861, 2019).
rheumatic diseases (1 paper, 2025). "Since DUSP10/MKP5 is involved in inflammatory regulation, the findings could have broader implications for other rheumatic diseases beyond cartilage degeneration, including those affecting synovial cells or the immune system." (PMID 40002789, 2025).
Stroke (1 paper, 2025). Sudden impairment of blood flow to a part of the brain due to occlusion or rupture of an artery to the brain. "Specifically, PPARα KO led to increased expression levels of Gadd45b, Nppa, Hdc, Lcn2, Il6, Sox4, Marcksl1, Saa3, Ucn2, Met, Dusp10, Elovl7, Ngf, C3, Il11, Hmox1, Alox5, Tnfsf9, Angptl4, Plin2, H19, Csf2rb, Atf3, and Col7a1 following stroke." (PMID 40362325, 2025).